CD4 (CD4 molecule)
Diseases named in the same sentence as CD4 in open-access papers (continued):
Sharing a sentence is not in itself a finding about the gene and the disease.
tumor (continued). "It was rather the lack of CD4 T cells in MHCII ko mice that mediated the favorable CTL effect, because transient depletion of CD4 T cells using CD4 T-cell depleting antibodies strongly facilitated CD8 T-cell responses as well as tumor remission." (PMID 31333674, 2019). "Co-administration of B16F10 cells with TTRAP enhanced tumor growth as compared to inoculation of B16F10 cells alone or co-administration with control CD4+ T cells." (PMID 31300052, 2019). "The residual population of tumor-infiltrating CD4+ T-cells exhibited reduced expression of the early activation marker CD69." (PMID 31188899, 2019). "Higher IL-12 expression was achieved through both an improved plasmid design, as well as reduced voltage and increased pulse length, which led to increased IFNγ and a higher CD8+/ CD4+ T-cell ratio with the tumor." (PMID 30323352, 2019). "It is likely that in addition to cytotoxic T cells, B cells and CD4+ T cells are required to mediate an immune response essential for tumor cell death, possibly for tumor antigen presentation or cytokine secretion." (PMID 30775178, 2019). "We and other authors have demonstrated that patients with GC have an increased prevalence of both circulating and tumor-infiltrating CD4+CD25+FoxP3+ Tregs in comparison to the healthy population." (PMID 31417548, 2019). "This analysis reveals that tumor-associated T cells contain activated CD8+ T cell states, but lack the presence of functionally activated CD4+ T cell states." (PMID 31624246, 2019). "We observed a positive clinical outcome in 30% of the patients, which correlated with increased tumor infiltration by CD4+ T cells." (PMID 31849934, 2019). "Although the percentages of IFN-γ-producing CD4+ T cells were slightly increased after B16-LX/IL-24 treatment, absolute numbers per tumor weight of these cells were significantly increased, compared with other groups." (PMID 31338417, 2019). "Here the authors show that replacing TGFβ with IL-1β induces a distinct IL-9+ CD4+ population that have strong cytotoxic and anti-tumor activity in preclinical mouse models." (PMID 30914642, 2019). "PEF2 (with and without Ca) treatment caused normalization of the levels of CD4 Tef/Tem cells in spleen, CD4 Tcm in spleen and LN, i.e., the percentage of mentioned cell subsets in treated mice was similar to that observed in tumor-free mice." (PMID 31717542, 2019). "In this study, we evaluated the anti-tumor effects and immunological responses induced by co-administration of HMGN1 and anti-CD4 depleting antibody intraperitoneally in Colon26 or B16F10 tumor-bearing mice." (PMID 30696484, 2019). "One hundred Nanograms per milliliter of IL-24 stimulation enhanced IFN-γ expression in both peripheral and tumor-infiltrating CD4+ T cells (Dunn's multiple comparison tests, P < 0.0001)." (PMID 31921658, 2019). "Here all tumor-infiltrating CD4+ or CD8+ T cells were CD44+, indicating that they were activated or possibly antigen-experienced." (PMID 31601678, 2019). "To determine the specific subtype of T cells involved in tumor regression, we implanted αKO cells in the pancreas of mice genetically engineered to lack CD4+ or CD8+ T cells (referred to as CD4KO or CD8KO mice, respectively)." (PMID 31112530, 2019). "Specifically, pDCs can effectively generate Tregs from naive CD4+ T cells, which contribute to tumor immune escape." (PMID 30936882, 2019). "On the other hand, B cells are vital elements in shaping an effective immune response by being efficient antigen-presenting cells (APCs) for the expansion of tumor-associated antigen-specific CD8+ and CD4+ T cells." (PMID 31554169, 2019). "We have shown that the amount of Tr1 (CD4+CD25−DX5+) and CD8+DX5+ increase in the spleens of tumor–bearing mice when compared with tumor-free mice (cells similar to conventional Treg (CD4+CD25+))." (PMID 31717542, 2019).
tumor (continued). "Overall, the mean and maximum tumor-to-heart ratios of 89Zr-DFO-CD4 and 89Zr-DFO-CD8a were in agreement with flow cytometric analysis of CD4+ and CD8a+ numbers across syngeneic mouse tumor models." (PMID 31754392, 2019). "As frequencies of ST2+ CD4+ FOXP3+ Tregs in CRC tissue correlated with tumor scores, we next performed a transcriptomic analysis to better understand the role of ST2 for Treg function during intestinal tumorigenesis." (PMID 31165767, 2019). "Nevertheless, CD4+ T cells appeared to infiltrate into HLA class II-positive areas within the tumour centre." (PMID 30377343, 2019). "Noteworthy, NFAT family proteins, are involved in cell transformation, proliferation, invasive migration, tumor cell survival, tumor angiogenesis and tumor-induced anergy of CD4+ T cells by mediating the expression of several inflammatory cytokines, as well." (PMID 31216652, 2019). "Analysis of the immune cells has identified CD4 + T cells as the predominant cell population within tumor microenvironment in cHL." (PMID 30783096, 2019). "While the main focus of basic and clinical research has been on improving CD8+ T cell-mediated eradication of tumor cells, the role of CD4+ T cells in tumor immunotherapy is much less developed." (PMID 31379821, 2019). "Our results emphasize a critical role of clonally expanded and antigen-experienced CD4+ T cells in tumor control." (PMID 31275310, 2019). "We also establish for the first time a link between frequency of ILCs and anti-tumor CD4 T cell responses in cancer patients." (PMID 31555301, 2019). "Not only do TIBs directly act on tumor cells, but they also indirectly regulate tumor immunity by affecting the function of other immune cells such as CD4+ T cells and Tregs and NK cells in tumor microenvironment." (PMID 31662750, 2019). "More relevant to time of day, some inflammatory mediators (Myd88, Cd4, Tlr9, Cd38, C3, Ly96) demonstrated nyctohemeral (day versus night) differences in control brain tissues that were abolished in tumor-bearing and/or tumor-resected mice." (PMID 31019214, 2019). "We found a significant difference in the CD4+ population on the tumor cell infiltrate between the six patients with pathological changes and those without pathological changes, respectively 50.91 ± 2.05% vs. 40.89 ± 2.26% (P = 0.006)." (PMID 31849934, 2019). "Because of PTX3 overexpression, tumor samples were also characterized by a significant reduction of CD4+ and CD8+ lymphocyte, mast cell and CD68+ macrophage pro-inflammatory populations." (PMID 31533326, 2019). "To further characterize the tumor infiltrate, we also measured the expression of PD-1 in CD4+ and CD8+ T cells, as well as the expression of OX40 in Tregs." (PMID 31428586, 2019). "This cell population, considered to be “chronically stimulated” CD4+ T cells, shares features observed in anergic cells from tumor-bearing mice, i.e., reduced proliferation ability and diminished cytokine production." (PMID 31750244, 2019). "Conversely, tumor growth rate, number of Treg clones, and density of naïve CD4 T cells in the blood correlated with percentage increase in tumor size." (PMID 31236847, 2019). "IDO expression was positively correlated with tumor‐infiltrating Foxp3 + Tregs (P < .001) as well as DC2s (P < .001), whereas it was negatively correlated with the tumor‐infiltrating CD4/CD8 + T cell ratio (P = .023)." (PMID 31631566, 2019). "Ex-vivo stimulation of tumor-infiltrating CD4+ and CD8+ memory T-cells (PMA/Ionomycin) revealed a prominent shift from a Th2 towards a Th1 phenotype with an increased intracellular ratio of IFN-γ to IL-4." (PMID 30506500, 2019). "mRNA expression corresponding to the component of IL-24 receptor, including IL-20R1, IL-20R2, and IL-22R1, was semi-quantified in peripheral and tumor-infiltrating CD4+ and CD8+ T cells." (PMID 31921658, 2019).
tumor (continued). "We performed a genetically engineered DC vaccine trial that induced polyclonal CD8+ and CD4+ antigen-specific T cell responses, as well as tumor regression or stabilization in several subjects." (PMID 31014399, 2019). "The PD-L1 pathway involves expression of PD-1 on activated T cells (both CD8+ and CD4+), and PD-L1 which is expressed on cancer cells as well as inflammatory cells of the tumor microenvironment including macrophages." (PMID 31134065, 2019). "The median fluorescence intensity of PD-1 (top), 4-1BB (middle), and TIGIT (bottom) were assessed by flow cytometry on CD8 (left) and CD4 (right) T cells from 39 patients who had evaluable flow cytometry data from baseline tumor samples." (PMID 30867072, 2019). "CD4+ Th1-oriented T cells are also important in promoting an anti-tumour immune response through the production of cytokines essential for T cell proliferation, as well as for macrophage recruitment and activation." (PMID 30413828, 2019). "In humans, the adoptive transfer of CD4+ T cells that recognize tumor-specific HLA class II-restricted neoantigens has been reported to show better tumor control in cancer patients." (PMID 30813491, 2019). "The post-trastuzumab tumor showed high immune activation with distinct nuclear staining of NF-κB/p65RelA in the majority of tumor cells alongside a higher number of CD4+ and CD8+ cells, and numerous immune cells expressing PD-1." (PMID 31618954, 2019). "Of note, such dual therapies were shown to not only augment intra-tumoral presence of DCs and tumor-specific CD8+ T cells but also the fraction of intra-tumoral CD4+ or CD8+ T cells producing IFNγ as well as the levels of IFNγ in the TME." (PMID 31244820, 2019). "In the distant tumor, the CD4+ T cell population was significantly higher following CPMV monotherapy and CPMV+CPA combination therapy, but the CD8+ T cell population was higher only following the CPMV+CPA combination therapy." (PMID 31453050, 2019). "In one aspect, some CD4 T cell subpopulations such as Th1 cells can exert anti-tumor immunity by overcoming the tolerance of autoantibodies expressed by tumors, and these effectors T cells are advantageous for tumor immunotherapy." (PMID 31632199, 2019). "In the context of head and neck squamous cell carcinoma, tumor-infiltrating CD4+CD25hiFoxp3+ T cells produce a higher level of TGF-β and reduced T cell proliferation more effectively than Treg cells from the periphery in Treg suppression assays." (PMID 31058083, 2019). "On the other hand, C5a has been reported to be required for the differentiation of naïve CD4+T cells into Th1 cells and for the homing of T cells to the tumor site." (PMID 31366131, 2019). "In contrast, CD4+ T cells and the subpopulation of immunosuppressive CD4+ Tregs increased only slightly in secondary lymphoid organs and the irradiated tumor." (PMID 30808414, 2019). "CTLA-4 is constitutively expressed by Tregs, but it can also be upregulated by other T-cell subsets, especially CD4-positive T-cells upon activation, as well as tumor cells." (PMID 31581738, 2019). "Flow cytometric analyses confirmed the weak infiltration with CD8+ or CD4+ T cells, but showed a massive invasion of M2 macrophages into the JA-0009 tumor (>70% of tumor infiltrating leukocytes)." (PMID 30791466, 2019). "CD4+IFNγ+ T cells were elevated in tumor in both CB-MSC monotherapy and combination treatment groups." (PMID 31320999, 2019). "Another anti-tumor role for TANs in mice and humans was uncovered with their implication in the recruitment and activation of intra-tumor CD4+ and cytotoxic CD8+ T cells." (PMID 31616408, 2019). "Since only 4% of tumor-infiltrating CD45+ cells are positive for CD4 and only 50% of those are Treg cells, the interactions between MDSCs and Treg cells are rare events to record and quantify." (PMID 32038621, 2019). "Nevertheless, CD4+ T cell help is critical for maintaining CD8+ T cell functions during anti-tumor response and chronic infection." (PMID 31156634, 2019).
tumor (continued). "This response to immune checkpoint therapy as well as relative CD4+ and CD8a+ tumor numbers in syngeneic tumor models were similar to reported elsewhere 54-57." (PMID 31754392, 2019). "Smaller tumor size was correlated with higher expression levels of peripheral CD4 + T cells (P = .003) and CD8 + T cells (P = .002), and lower IDO expression (P = .044) in tumors." (PMID 31631566, 2019). "Although it has been confirmed that some of the neoantigen-specific CD4+ T cells are able to kill tumor cells, the majority of tumor-specific killer T cells identified in patients have been of CD8+ T cells origin." (PMID 31749795, 2019). "The therapeutic potential of host-vs.-tumor activity has been analyzed by various groups and is based on CD4+ and CD8+ T cell responses, which are part of the cancer immune cycle and significantly influence the clinical outcome of patients." (PMID 31555274, 2019). "Generally, CD8+ T cells are considered as effector cells to destroy cancer cells, whereas the roles of anti-tumor CD4+ T cells are to provide CD4-help to other immune effector cells such as CD8+ T cells through cytokine production and CD40-CD40L ligation." (PMID 30626427, 2019). "Tumor bearing Stat4−/− mice showed trends toward decreases in CD4+ and CD8+ cells in lymph nodes and spleens, which was more pronounced in metastatic cases." (PMID 32010142, 2019). "(C) Representative (left) or statistical histograms (right) showing the percentage of Tregs within CD45+ CD4+ cells in the tumor microenvironment (n = 6)." (PMID 31511064, 2019). "These alarmins at the irradiated tumor bed trap injected eMIP and, by forming complexes with eMIP, play a key role to recruit and activate tumor inhibitory natural killer (NK) cells and CD4+ and CD8+ T cells." (PMID 31058025, 2019). "Tumor-derived vascular pericytes induce CD4 T cell inactivation/dysfunction, which is thought to influence immune surveillance during continuous tumor growth." (PMID 31205449, 2019). "Tumors (Cd4, tendency in Myd88, p = 0.07) and tumor resection (Myd88, Cd4, Tlr9, Cd38) eliminated these time-of-day differences by reducing light-phase gene expression relative to controls and or increasing dark phase expression." (PMID 31019214, 2019). "In contrast, tumor-bearing mice receiving SLA–OVA alone had CD4+ T cells at the tumor margin but very few CD8+ T cells." (PMID 31771150, 2019). "In this part of the clinical specimens, CD4+ T‐cell infiltration in the tumor area was significantly increased." (PMID 31018021, 2019). "Conversely, expression of IL-1β by MDSCs in response to either gemcitabine or 5-FU was demonstrated to induce IL-17 expression by CD4+ T cells, which suppressed the chemotherapy-dependent control of tumor growth." (PMID 31379850, 2019). "In the same patient, the CD4/CD8 DP population retained major histocompatibility complex (MHC) class I restricted activity against autologous tumor cells." (PMID 30709425, 2019). "The drivers and the specification of CD4+ T cell differentiation in the tumor microenvironment and their contributions to tumor immunity or tolerance are incompletely understood." (PMID 30926808, 2019). "In a mouse model of melanoma, IDO+ pDCs derived from tumor-draining lymph nodes were reported to stimulate CD4+CD25+Foxp3+ Tregs." (PMID 30987228, 2019). "In a mouse model of breast cancer, it was also shown that CCL21 recruits CCR7-expressing ILC3s with an LTi phenotype (CD4+CCR6+) to the tumor environment." (PMID 31507605, 2019). "The inhibition of tumor growth and metastasis in mice treated with anti-CD4 (αCD4), anti-CD8 (αCD8) and anti-CD49b (αNK) antibodies, was reduced compared with that in non-depleted mice." (PMID 31431623, 2019). "To determine if tritherapy increased tumor-specific CD4+ T cells in the tumor, we used BALB/c Nur77GFP reporter mice." (PMID 31747946, 2019). "Studies have shown that tumor-specific CD4+ T cells have complex roles beyond supporting CD8+ T cells." (PMID 31540435, 2019).
tumor (continued). "Our cellular ablation experiments using CD11c.DTR mice suggested that, as a bulk population, DC are tumor permissive in PDA in a CD4+ T-cell-dependent manner." (PMID 30926808, 2019). "It was also found that the number and function of CD4+/CD25+/FoxP3+ Tregs in the lymph nodes, spleen, and tumor tissue are reduced in the B-cell-deficient mouse model, resulting in significant inhibition of tumor development." (PMID 31662750, 2019). "Detailed analysis of tumor cell populations revealed an ~ 8-fold increase in CTLs and an ~ 3-fold increase in CD4+ T cells following domatinostat treatment." (PMID 31703604, 2019). "MHC-II molecules are critical for antigen presentation to CD4+ T-lymphocytes and its role in anti-tumor immunity is increasingly appreciated." (PMID 31212865, 2019). "In lymphopenic murine hosts, tumor-specific CD4 TRM had cytotoxic activity active against established melanoma tumor." (PMID 30669682, 2019). "An early study focusing on the interaction between SCLC cells and their TME showed how SCLC tumor cell lines were able to inhibit activated CD4+ T-cells." (PMID 31383005, 2019). "A high CD4/Treg ratio indicates a low ratio of Treg cells among CD4+ T cells and a high ratio of T helper cells that support anti-tumor immunity." (PMID 30971280, 2019). "Like the B16-OVA, IR alone induced a significant increase in tumor-infiltrating FoxP3+CD4+ Tregs and a decrease in the ratio of CD8+ T/Tregs in the irradiated lung." (PMID 31704921, 2019). "In this regard, we have characterized MHC class II-restricted CD4+ T cells that have potent anti-tumor activity by direct recognition of human cancer cells in a MHC class II-restricted manner." (PMID 30626427, 2019). "Their research showed that the Songyou Yin (SYY) compound statistically significant reduced tumor growth as well as raised the CD4+ to CD8+ ratio." (PMID 30805305, 2019). "The subversion of the tumor microenvironment affected also the number CD4+/CD25+ regulatory T cells (Tregs) in draining lymp nodes." (PMID 31417570, 2019). "To further interrogate the phenotype of the infiltrating T cells, we analyzed expression of PD-1 on tumor-infiltrating CD4+ and CD8+ T cells." (PMID 31892360, 2019). "In that context as well, tumor infiltrating lymphocytes (TIL) (CD4+ and CD8+) are emerging as potential independent prognostic factors for overall survival (OS) and response rate (RR) regarding ICI treatment." (PMID 31590386, 2019). "In one study, tumor-specific CD8 T cells were activated independently of CD4 T cells, but required Th1-polarized CD4 T cells for effective tumor suppression." (PMID 31333674, 2019). "Regulatory T cells are an important CD4+ T cell subtype that can impact anti-tumor immune responses." (PMID 31417550, 2019). "IL-10 produced by tumor-infiltrating myeloid cell and Foxp3+ CD4+ regulatory T cells (Treg) is a major tolerogenic cytokine that downregulates IFN-I expression in pDC." (PMID 30979057, 2019). "APG-115 as a single agent plays multiple roles in modulating immune responses, including increasing T cell proliferation, enhancing CD4+ T cell activation, upregulating PD-L1 expression on tumor cells, and increasing M1 macrophages either in vitro or in vivo." (PMID 31779710, 2019). "B regulatory cells (Bregs), a subset of B cells, and tumor-associated macrophages (TAMs) reduce the activity of cytotoxic CD8+ and CD4+ T effector cells by releasing anti-inflammatory cytokines like IL-10 and by expressing coinhibitory molecules." (PMID 31949880, 2019). "This increased expression, through the enhancement of T-helper 1 (Th1) effector functions, promotes CD4 cell infiltration and activation which, in turn, leads to tumor regression." (PMID 31762942, 2019). "These channels were shown to be necessary for DC-mediated activation of both CD4+ T cells and NK cells, as well as for the efficient NK cell-mediated tumor cell killing." (PMID 31547237, 2019).